CRP (C-reactive protein)
Diseases named in the same sentence as CRP in open-access papers (continued):
Sharing a sentence is not in itself a finding about the gene and the disease.
Thrombocytopenia (continued). "Specific baseline lab values, including thrombocytopenia and elevated C-reactive protein (CRP), have been associated with CRS and ICANS on a univariate level and in combination with LDH in the modified EASIX (Endothelial Activation and Stress Index) score for adult patients with B-ALL and DLBCL." (PMID 39674824, 2024). "Clinical features, including mucocutaneous and enteric symptoms, thrombocytopenia, and a significantly elevated CRP associate with PIMS-TS, which may aid diagnosis, and rapid commencement of effective therapy." (PMID 38027272, 2023). "While some suggest elevated levels of c-reactive protein (CRP), d-dimer, and thrombocytopenia increase the risk of death among male patients, others have shown that inflammatory biomarkers may be more reliable in predicting death in women." (PMID 36224551, 2022). "The degree of thrombocytopenia as observed in the current study was concordant with inflammation, as severe thrombocytopenia has been significantly associated with marked elevation in the inflammatory markers, including CRP and SAA, in previous studies." (PMID 35626194, 2022). "These organ failures may be associated with a CRS characterized by high fevers, thrombocytopenia, hyperferritinemia, and elevation of other inflammatory markers including C-reactive protein (CRP)." (PMID 33024459, 2020). "Recent studies have reported that low lymphocyte-to-C-reactive protein ratio, platelet-to-lymphocyte ratio, and thrombocytopenia may be associated with critical illness." (PMID 32434518, 2020). "However, thrombocytopenia has shown to be associated with the severity of inflammation, e.g., expressed as a C-reactive protein (CRP), and severity of capillary leakage in acute PUUV infection." (PMID 30974852, 2019). "The febrile illness associated with leukopenia, thrombocytopenia, an elevated concentration of serum C-reactive protein, and the demonstration of A. phagocytophilum infection by seroconversion as well as a positive PCR result also met the criteria for confirmed HGE." (PMID 15757574, 2005). "In addition, we found thrombocytopenia and high CRP levels to be associated with mortality." (PMID 28149700, 2017). "High plasma IL-6 was also found to be an independent risk factor for thrombocytopenia and hospitalization exceeding seven days (OR 3.6, 95% CI 1.6-8.0, P = 0.002, and OR 4.5, 95% CI 1.9-10.8, P < 0.001, respectively) in models including high plasma IL-6, high plasma CRP, and age." (PMID 20500875, 2010). "His condition initially improved, with fever resolution and decreased CRP, but thrombocytopenia persisted." (PMID 39802943, 2025). "When available, laboratory investigations showed leukopenia, thrombocytopenia, and raised lactate dehydrogenase, C-reactive protein, and liver enzymes (alanine aminotransferase, aspartate aminotransferase, and gamma glutamyl transaminase) as main findings." (PMID 39715072, 2025). "Laboratory abnormalities, including thrombocytopenia, elevated C-reactive protein (CRP) and lactate dehydrogenase (LDH), and hyponatremia (45.5%; 133 ± 6.95 mmol/L), were frequently associated with surgical NEC." (PMID 41294908, 2025). "Even in the absence of tick bite marks, clinicians should suspect SFTS in patients presenting with fever, thrombocytopenia, a slight elevation of serum CRP levels, and elevated liver enzymes—especially when there is a history of contact with cats." (PMID 41143065, 2025). "•SFTS presents with thrombocytopenia, elevated transaminases, and a slight elevation of C-reactive protein." (PMID 41143065, 2025). "Common clinical features included fever, thrombocytopenia, and a slight elevation of serum C-reactive protein (CRP) levels." (PMID 41143065, 2025). "Occurrences of metabolic acidosis, thrombocytopenia, neutropenia, and peak CRP were comparable between early and late onset GBS sepsis." (PMID 39825283, 2025). "Laboratory tests revealed hypochromic microcytic anaemia, thrombocytopenia, and elevated C-reactive protein (CRP)." (PMID 40677499, 2025).
Thrombocytopenia (continued). "His laboratory investigations revealed a normal white blood cell count, thrombocytopenia, a mildly raised C-reactive protein, and positive dengue IgM serology." (PMID 41245666, 2025). "Laboratory findings during the active phase of CTB revealed statistically significant elevations in C-reactive protein levels (P = 0.001), thrombocytopenia (P = 0.007), hyponatremia (P = 0.040), hypocalcemia (P = 0.022), and hypomagnesemia (P = 0.025)." (PMID 41262922, 2025). "At 3 months of age, the infant developed septic shock, with thrombocytopenia and elevated inflammatory markers (C-reactive protein (CRP) 148 mg/L, procalcitonin (PCT) >100 ng/mL, interleukin-6 (IL-6) 20,000 pg/mL)." (PMID 40723093, 2025). "Observations of thrombocytopenia and elevated C-reactive protein together with decrease in lymphocytes and platelets, and increase in neutrophils within the blood." (PMID 40195851, 2025). "CRP elevation and transient thrombocytopenia can occur with SDRs, in contrast to the abrupt, severe thrombocytopenia that characterizes immune-mediated rifamycin reactions." (PMID 41333648, 2025). "In diabetics, active smokers presented with higher rates of thrombocytopenia (22.4% vs. 9.1%, p = 0.02) and elevated CRP (30.6% vs. 14.9%, p = 0.01)." (PMID 41303252, 2025). "For instance, even simple host markers like elevated C-reactive protein and thrombocytopenia have shown surprisingly robust correlations with severe malaria in both immune and non-immune populations, making them useful starting points for point-of-care tests." (PMID 41002937, 2025). "Laboratory findings included thrombocytopenia, elevated liver enzymes, and increased C-reactive protein (CRP)." (PMID 40970053, 2025). "The most frequent laboratory abnormalities among paediatric cohort PLWH were dyslipidaemia (37%), cholestasis (26%), cytolysis (17%), elevated C-reactive protein (15%), and thrombocytopenia (10%)." (PMID 41471216, 2025). "Rickettsiosis was characterized by high-grade fever, rash, headache, thrombocytopenia, elevated C-reactive protein (CRP), and gastrointestinal, respiratory, and neurological symptoms." (PMID 40094918, 2025). "Initial laboratory findings, demonstrated severe leukopenia, thrombocytopenia, acute renal failure, and an elevated inflammatory response with high levels of CRP and procalcitonin." (PMID 40070620, 2025). "All patients exhibited thrombocytopenia, elevated liver enzymes, and a slight elevation of serum C-reactive protein." (PMID 41143065, 2025). "Abnormal laboratory markers, including increased CRP, thrombocytopenia, and metabolic acidosis were observed in similar frequency in EOGBSS and LOGBSS." (PMID 39825283, 2025). "For instance, a rash, hyponatremia, thrombocytopenia, and elevated CRP suggest rickettsiosis, warranting doxycycline treatment." (PMID 40094918, 2025). "After NICU admission, the neonate had multiple episodes of fever, thrombocytopenia, raised C-reactive protein (177.9 mg/L, reference range 0-5 mg/dL), and raised CSF cell cytology (150 cells/μL, 65% neutrophils, reference range 0-32cells/μL)." (PMID 40861657, 2025). "They exhibited high levels of C-reactive protein (CRP), neutrophilia, thrombocytopenia, and elevated biochemical markers indicative of liver and kidney dysfunction, which are typical of leptospirosis." (PMID 40986630, 2025). "The variables used included altered mental status, leukopenia (white blood cell count <4000/μL), thrombocytopenia (platelet count <1 × 103/μL or 80 × 103/μL), a prolonged activated partial thromboplastin time (>35 seconds), and a normal CRP level (≤1.0 mg/dL)." (PMID 40922296, 2025). "High CRP levels were found to be a significant independent risk factor for severe ROP and add to thrombocytopenia risk, especially in control infants." (PMID 39702768, 2025).
Thrombocytopenia (continued). "In cases of transmural injury, laboratory signs of shock are typically present, such as pronounced neutrophilic leukocytosis, markedly elevated C-reactive protein, severe metabolic lactic acidosis, azotemia, hepatocellular injury, and thrombocytopenia." (PMID 41375878, 2025). "In this intriguing case, the presence of initial flu-like symptoms, thrombocytopenia, and elevated CRP on blood tests, coupled with the eschar resembling tick bites, led the clinician to diagnose rickettsiosis." (PMID 41246602, 2025). "Laboratory findings revealed leukopenia (3.78 × 109/L), elevated neutrophil ratio (85.2%), reduced lymphocyte ratio (9.9%), thrombocytopenia (91 × 109/L), and elevated inflammatory markers (CRP: 156.06 mg/L; high-sensitivity CRP: >5.00 mg/L)." (PMID 41366987, 2025). "Laboratory findings showed elevated C-reactive protein (100%), thrombocytopenia (94.9%), leukopenia (59.0%), and cytolysis (66.7%)." (PMID 41490466, 2025). "In previous studies on prognostic factors in HFRS that included more than 100 patients, several laboratory variables—C-reactive protein, total bilirubin, albumin, thrombocytopenia, and proteinuria—were reported as significant prognostic markers." (PMID 40072771, 2025). "Blood tests were remarkable for thrombocytopenia, elevated C-reactive protein (CRP), discrete elevated liver enzymes (cytocholestatic pattern), and elevated lactic dehydrogenase (LDH)." (PMID 40109780, 2025). "Further examination revealed thrombocytopenia (platelet count 4.7×104/μL), severe renal dysfunction (creatinine 2.56 mg/dL), and systemic inflammation (C-reactive protein 18.52 mg/dL)." (PMID 40201884, 2025). "Almost all (97.4%, 38/39 cases) patients in our study had fever and thrombocytopenia (94.9%, 37/39 cases), and all had elevated CRP levels within 7 days after tick bite." (PMID 41490466, 2025). "Elevated CRP levels and thrombocytopenia were the most frequent abnormal laboratory findings and were observed in almost all cases." (PMID 41490466, 2025). "For example, both MAS and severe or atypical infections often present with leukopenia or thrombocytopenia, high CRP or ferritin levels, and hemorrhagic or hepatic problems." (PMID 39062205, 2024). "Laboratory findings, such as elevated CRP, thrombocytopenia, and coagulopathy, highlight the severity of the error and underscore the importance of timely recognition and intervention." (PMID 39659317, 2024). "The disease course is usually accompanied by pathological laboratory findings, including leukopenia and thrombocytopenia, as well as C-reactive protein (CRP), urea, creatinine and liver transaminase elevation." (PMID 38792596, 2024). "Initial laboratory investigation revealed a high serum C-reactive protein, a high serum procalcitonin, leucopenia, thrombocytopenia, and hyponatremia." (PMID 38957821, 2024). "The complications of typhoid fever include leucopenia and thrombocytopenia accompanied by elevated C-reactive protein (CRP) and alanine aminotransferase (ALT) levels." (PMID 39200066, 2024). "Initial blood work showed a mild thrombocytopenia, normal renal function, elevated inflammatory markers, with C reactive protein (CRP) of 27.6 mg/dL." (PMID 39749054, 2024). "Hospitalized HFRS patients showed a typical clinical presentation during the acute phase, with thrombocytopenia, elevated C-reactive protein (CRP) and plasma creatinine levels, and viremia." (PMID 39038044, 2024). "Blood samples revealed high serum C-reactive protein and procalcitonin, leucopenia, thrombocytopenia, hyponatremia, hepatic cytolysis, and cholestasis." (PMID 38957821, 2024). "Blood tests resulted in thrombocytopenia (131 × 103/μL) and C reactive protein (CRP) was 7.2 mg/dL (0–0.5 mg/dL)." (PMID 39252311, 2024). "Investigations showed leucocytosis, thrombocytopenia, abnormal liver function tests, renal dysfunction, and elevated C-reactive protein." (PMID 38903293, 2024).
Thrombocytopenia (continued). "The laboratory findings were elevated lactate dehydrogenase and C-reactive protein in 100% of patients, elevated ferritin in 92.9%, thrombocytopenia in 71.4%, elevated AST and ALT in 71.4%, and elevated D-dimer in 57.1% of patients." (PMID 39345300, 2024). "The laboratory work-up revealed mild thrombocytopenia, mild hyperproteinemia with hyperglobulinemia, a marked elevation of the c-reactive protein, and decreased iron concentration." (PMID 39681858, 2024). "The patients’ symptoms included classic HFRS symptoms, such as fever, general malaise, nosebleed, and renal insufficiency, and laboratory results indicated thrombocytopenia and a moderately increased C-reactive protein." (PMID 38526134, 2024). "This diagnosis was accompanied by thrombocytopenia, hyperglobulinemia, elevation of CRP, and a decrease in iron concentration." (PMID 39681858, 2024). "Thrombocytopenia is also common, along with increased levels of D-dimer and inflammatory markers such as C-reactive protein (CRP), erythrocyte sedimentation rate (ESR), interleukin-6 (IL-6), and procalcitonin." (PMID 39599799, 2024). "Her temperature kept fluctuating despite treatment with antibiotics, lethargy and difficulty in drinking persisted, and thrombocytopenia worsened to a minimum of 11 × 109/L on day 6, with a peak CRP of 9 mg/L." (PMID 37744436, 2023). "Patient 3 was started on etanercept at the age of 4 months and had partial improvement of systemic inflammation (CRP), thrombocytopenia, and direct hyperbilirubinemia but had persistently elevated LFTs." (PMID 36932076, 2023). "The main laboratory findings on admission were leukopenia (WBC 800/mm3), thrombocytopenia (Plt count 78.000/mm3), elevated urea, creatine levels and increased inflammatory markers (CRP 368 mg/ml)." (PMID 37674134, 2023). "The laboratory findings showed mild thrombocytopenia, elevated, but decreasing c-reactive protein, and modified coagulation tests (due to ongoing anticoagulation treatment)." (PMID 37510971, 2023). "No relevant signs were found, except for a few abnormal biochemical tests, including thrombocytopenia (counts of platelets = 34 × 109/L), increased C-reactive protein (CRP, 88.1 mg/L), and weakly positive tuberculosis-interferon gamma release assay." (PMID 37443058, 2023). "In the thrombocytosis group and normal platelet count group, MPV, CRP, and LD levels were lower than those in the thrombocytopenia group." (PMID 37312072, 2023). "The main laboratory findings on admission were as following: leukopenia (WBC 800/mm3), thrombocytopenia (Plt count 78,000/mm3), elevated urea, creatine levels and increased inflammatory markers (CRP 248 mg/ml)." (PMID 37674134, 2023). "Similar to thrombocytopenia, persistently elevated CRP in NEC infants made a case for surgical intervention." (PMID 36793334, 2023). "Laboratory studies showed thrombocytopenia (60x109/l), normal CRP, high ESR (34mm/h) and liver enzymes (ALT 2059IU/l, AST 674IU/l, GGT 220IU/l), low albumin (30.1g/l) and increased levels of creatin-kinase (CK) (1148IU/l)." (PMID 37848930, 2023). "Three days after weaning from ECMO support, steroids and therapeutic plasma exchange were initiated due to deteriorating thrombocytopenia, oxygenation, hemodynamic instability, and increased C-reactive protein (CRP) and ferritin levels." (PMID 37842348, 2023). "Neutropenia, thrombocytopenia, metabolic acidosis, and elevated CRP levels are common signs in infants with NEC.7 8 The great majority of surgeons indeed relied on these parameters for the assessment of severity in our study." (PMID 37575368, 2023). "Our findings suggest that not only atypical clinical symptoms such as the lack of epigastric pain but also laboratory findings such as thrombocytopenia and higher serum CRP level can be characteristics of older patients with AA." (PMID 35004106, 2022).
Thrombocytopenia (continued). "A C-reactive protein (CRP) >10 mg/dl was found in 28/169 patients (16%), neutropenia was reported in 30/180 patients (16%) and moderate thrombocytopenia (<100,000) was found in 12 patients (7%)." (PMID 35757135, 2022). "In our case, both patients presented thrombocytopenia, elevated transaminases, and increased CRP, making differentiation difficult from the clinical approach point of view." (PMID 35568905, 2022). "Especially, recovery in the main infection indicators (e.g., lymphocytopenia, thrombocytopenia, elevated CRP, and hypokalemia) and myocardial biomarkers (e.g., CPK, CK-MB, and LDH) exhibited good convalescence." (PMID 36062112, 2022). "Five criteria, CRP >11 mg/dl (18 points), D-dimer >607 ng/ml (27 points), age >5 years (30 points), thrombocytopenia (25 points), and GI involvement (28 points), were included in the score." (PMID 36471327, 2022). "Only 17 (4.04%) of the 421 individuals had thrombocytopenia 79.10% of 421 serum C-reactive protein results were in the normal range." (PMID 35997401, 2022). "The patient's initial presentation was consistent with septic shock, including elevated CRP level, thrombocytopenia, hyperbilirubinemia, renal insufficiency, and refractory shock." (PMID 35414928, 2022). "At two years and seven months after CBT, he was admitted to our hospital with fever, thrombocytopenia, renal insufficiency, and elevated levels of bilirubin and C-reactive protein." (PMID 35505736, 2022). "His blood tests revealed leucocytosis (9280/μL), thrombocytopenia (77000/μL), elevated CRP levels (11.09 mg/dL), and elevated procalcitonin levels (0.94 ng/mL)." (PMID 35606754, 2022). "We conclude that unusually high C-reactive protein, neutrophilia, and thrombocytopenia serve as supplemental laboratory indicators for early identification of KDSS in patients with NFKD." (PMID 35053681, 2022). "Thrombocytopenia elevated D-dimer, and IL-6 were found among RT-PCR patients, whereas CRP, NLR, and ferritin were found among RT-PCR-negative patients." (PMID 36532907, 2022). "After treatment, most hematological parameters were ameliorated, such as lymphocytopenia, thrombocytopenia, and elevated levels of D-dimer, CRP, PCT, ALT, AST, and ALP." (PMID 36062112, 2022). "Higher level of CRP was demonstrated in patients with thrombocytopenia at 1–10 days, 11–20 days and 21–30 days after symptom onset, and with significant difference at 11–20 days compared to the non-thrombocytopenia group." (PMID 35791362, 2022). "Elevated levels of inflammation markers, including interleukin 6 (IL-6), tumor necrosis factor α (TNF-α), C-reactive protein (CRP) and procalcitonin, were observed at 1–10 days or 11–20 days after symptom onset in the patients with thrombocytopenia." (PMID 35791362, 2022). "These facts have led to the rating of positive urine cultures, similar to blood ones, and the use of surrogate tests including thrombocytopenia and elevated C-reactive protein as predictors of candidemia in infants." (PMID 35740125, 2022). "The patient presented mild leukocytosis with neutrophil predominance, moderate thrombocytopenia, elevated CRP and serum IgG amount, prolonged active prothrombin time, anti-DNA Ab, anti-ribosomal P antibody and marked reduction of complement activity." (PMID 35361277, 2022). "Laboratory test results, such as increased or decreased white blood cell count, thrombocytopenia, metabolic acidosis, unstable glucose levels, and elevated C-reactive protein levels, can be observed in patients with NEC." (PMID 34980023, 2022). "Low lymphocyte-to-C-reactive protein ratio, low platelet-to-lymphocyte ratio, and thrombocytopenia have been observed in critical SARS-CoV-2 infections." (PMID 36187170, 2022). "Laboratory abnormalities including NT-proBNP, troponin-T, lymphocytopenia, thrombocytopenia, and C-reactive protein (CRP) appear to return to normal ranges by 1–4 weeks post discharge." (PMID 35433557, 2022).